IL25 (interleukin 25)
Diseases named in the same sentence as IL25 in open-access papers (continued):
Sharing a sentence is not in itself a finding about the gene and the disease.
colitis (continued). "Our results are contrary to a previous study showing that exogenous IL-25 had an inhibitory effect on the development of DSS colitis." (PMID 25937893, 2014). "There are, however, inconsistent reports regarding the role of IL-25 in the development of colonic inflammation." (PMID 25937893, 2014). "In order to look for the involvement of IL-25 in gut inflammation we used the oxazolone model of colitis, known by its clear type-2 immune phenotype." (PMID 22539101, 2012). "Neutralizing antibodies to IL-25 or IL-17BR were administered to mice with oxazolone-induced colitis, a model of ulcerative colitis." (PMID 22539101, 2012). "In type-1 responses, such as in DSS and TNBS colitis, IL-25 clearly plays an anti-inflammatory role." (PMID 22539101, 2012). "In previous studies, IL-25 was shown to have a protective effect towards the development of colitis by down-regulating IL-12 and IL-23, which, in turn, limits the Th1-driven inflammatory response." (PMID 22539101, 2012). "We demonstrate that IL-25 plays a critical role in mediating intestinal type-2 inflammation in oxazolone colitis and that, in contrast to the DSS and TNBS type-1 models, it acts as a pro-inflammatory cytokine." (PMID 22539101, 2012). "Neutralizing IL-25 prior to the onset of colitis almost completely reversed the physical symptoms of disease." (PMID 22539101, 2012). "IL-25 plays a pro-inflammatory role in the oxazolone colitis model, and neutralizing antibodies to IL-25 or IL-17BR can slow the ongoing inflammation in this disease." (PMID 22539101, 2012). "We found that in oxazolone colitis IL-25 production derives from intestinal epithelial cells and that IL-17BR+ IL-13-producing natural killer T (NKT) cells and nuocytes drive the intestinal inflammation." (PMID 22539101, 2012). "Furthermore, the IL-17B deficiency was found to be pathogenic for Citrobacter rodentium infection, which resembled DSS-induced colitis, whereas Il25−/− mice were protected against Citrobacter rodentium infection." (PMID 37005677, 2023). "However, our previous research showed that deletion of IL25 in C57BL/6J protected from DSS-induced colitis." (PMID 35359953, 2022). "Interleukin-25 (IL17E/IL25) plays a critical role in colitis and intestinal homeostasis." (PMID 35359953, 2022). "IL-25 blockade led to increased colitis and correlated with reduced colonic eosinophils." (PMID 36263033, 2022). "IL-25 has also been shown to promote inflammatory responses in the context of colitis, suggesting that it might favor tumor development." (PMID 36032129, 2022). "As the type 2 immune response has been shown to be closely related to the pathogenesis of UC, OXA-induced colitis is considered a suitable model, and blocking the IL-25 signal of ILC2 may contribute to the remission of oxazolone-induced colitis." (PMID 36032134, 2022). "It is essential that the exact role of IL‐25 in colitis needs further investigation." (PMID 35593111, 2022). "IL-25 had a protective role against E. histolytica colitis in the mouse model." (PMID 28246365, 2017). "Because of the importance of the microbiome and the intestinal epithelium in defense against E. histolytica colitis (26, –, 28), we hypothesized that IL-25 would be protective against amebic infection in the cecum." (PMID 28246365, 2017). "Most recently, the protective effects of H. diminuta infection, and of the myeloid population induced by the parasite, have been shown to be inhibited by IL-22, but promoted by IL-25, with disease scores in DNBS-induced colitis exacerbated by anti-IL-25 antibody treatment." (PMID 28302598, 2017). "We hypothesized the increased IL-25 in colitis, resulting in type-2 inflammation, would create an environment more favorable for tumor growth and development." (PMID 27165713, 2016). "However, when we applied this same approach to an established murine model of colitis induced colon cancer, the tumor development surprisingly increased when mice were treated with an IL-25 blocking antibody." (PMID 27165713, 2016).
colitis (continued). "Our studies suggest that using an α-IL-25 antibody as a therapeutic approach could have adverse effects in colitis patients whereby it actually promotes tumorigenesis." (PMID 27165713, 2016). "The same report also showed that exogenous IL-25 ameliorated mouse TNBS colitis that features up-regulation of pro-inflammatory Th1 cytokines as seen in CD, or oxazolone colitis that has histological characteristics and elevated production of type 2 cytokines resembling UC patients." (PMID 25937893, 2014). "We next utilized a model of chronic DSS-induced colitis to further evaluate the role of IL-25." (PMID 25937893, 2014). "The observed resistance to DSS-induced colitis in IL-25−/− mice led us to investigate whether this was related to defective IL-13 expression." (PMID 25937893, 2014). "In contrast to IL-25−/− mice, IL-13−/− mice were more susceptible to DSS-induced colitis." (PMID 25937893, 2014). "We cultured T84 cells, a human colonic epithelial cell line, to determine whether IL-25 directly stimulates epithelial cells to produce pro-inflammatory cytokines that may contribute to colitis." (PMID 25937893, 2014). "In contrast, mice deficient in IL-13 are more susceptible to the colitis indicating the protection conferred by IL-25 deficiency is unlikely due to a lack of IL-13." (PMID 25937893, 2014). "In addition, a variety of agents such as FK506-entrapped nanoparticles, viral and nonviral NF-κB decoys, blockade of CD30-CD30L interaction, IL-25, leptin, and a plant-derived compound have been shown to ameliorate both colitis models." (PMID 24348533, 2013). "We demonstrate a novel role for IL-25 as a pro-inflammatory cytokine in a type-2 model of colitis." (PMID 22539101, 2012). "This experiment suggested that IL-25 could exacerbate the severity of DSS-induced colitis." (PMID 37005677, 2023). "However, IL-17B and IL-25 appear to have opposite functions in colon inflammation." (PMID 38068860, 2023). "Furthermore, IL-25 treatment could reduce partially the TNBS-colitis histologic scoring, suggesting that IL-25 may limit inflammation development by reducing IL-12 and IFNγ protein expression and cellular infiltration to the mucosa." (PMID 34581755, 2021). "Therefore, in inflammatory conditions, such as colitis, the production of IL‐25 and IL‐25R might be favorable for CRC inhibition." (PMID 34128588, 2021). "Therefore, we asked whether blocking IL-25 via neutralizing antibodies against the ligand or its receptor IL-17BR could protect against inflammation in an oxazolone-induced mouse model of colitis." (PMID 22539101, 2012). "For example, oral berberine activates bitter taste receptor signaling, promoting tuft cell differentiation and secretion IL-25, which initiates a type 2 immune response, thereby ameliorating DSS-induced colitis through ILC2 and Th2 cell modulation." (PMID 41041315, 2025). "IL-25 was also found to ameliorate experimental TNBS- and dextran sodium sulfate (DSS)-induced colitis by inhibiting TH17 cells." (PMID 34581755, 2021). "Our study confirms the interaction between mmu-miR-691/mmu-miR-135b-5p and Il25, indicating the role of mmu-miR-691 and mmu-miR-135b-5p in protecting against gut inflammation in the context of DSS-induced colitis." (PMID 32779953, 2020). "While colitis studies generally focus on shorter time-points post DSS treatment for evaluation, mouse colons assessed after long-term blockade of IL-25 revealed an increased colitis score compared to control mice." (PMID 27165713, 2016). "Our current study showed that direct stimulation of a cell line of colonic epithelial cells with IL-25 increased expression of IL-6, TNFα, as well as IL-8 and CCL2, providing a potential mechanism by which IL-25 contributes to DSS-induced colitis." (PMID 25937893, 2014). "Given that there is a strong correlation between colitis and CRC, we hypothesized that IL25 was continuously upregulated in CRC and promoted cancer development." (PMID 35359953, 2022).
colitis (continued). "IL-25 is expressed in both the colon and specific macrophage and epithelial cells located in the gut3, 7, is detected in the colons of mice under steady-state conditions, and is significantly elevated upon acute exposure to a DSS-induced colitis model." (PMID 27165713, 2016). "Overall, these results suggest that mice deficient in IL-13 have increased susceptibility to acute DSS-induced colitis, ruling out the possibility that the decreased susceptibility to DSS-induced colitis in IL-25−/− mice is due to a lack of IL-13." (PMID 25937893, 2014). "Last but not least, outside of colitis, much less is known about the roles of IL25 in CRC." (PMID 35359953, 2022). "However, it is likely that the protection against colitis exhibited by H. diminuta and partly mediated by IL-25 occurs independent of MC." (PMID 30670631, 2019). "Nuocytes have been described recently as a new innate cell type that is responsive to IL-25 and is the main producer of IL-13 in the gut during helminth parasite infection and here we found for the first time the presence of this new type-2 innate lymphoid cell (ILC) during inflammation in colitis." (PMID 22539101, 2012). "Therefore, because IL-25 is known for driving IL-13 production by IL17BR+ cells and for inducing type-2 inflammation in the lung and gut, we hypothesized that IL-25 might have a pro-inflammatory role in the type-2 model of colitis." (PMID 22539101, 2012). "Results from this study showed reduced colitis in mice genetically lacking IL-25 after exposure to DSS, thus providing evidence that endogenous IL-25 may have a pro-inflammatory role in the development of colonic inflammation." (PMID 25937893, 2014).
parasitic infection (34 papers, 2015 to 2025). "A parasitic infection triggers the secretion of interleukins, particularly interleukin 25 (IL-25), which, in turn, causes the secretion of interleukin 13 (IL-13), which is responsible for goblet cell hyperplasia and mucin production." (PMID 34836095, 2021). "To investigate the role of IL-25R in generation of innate and adaptive type-2 responses following chronic parasite infection, we used mice deficient in the IL-25-specific receptor subunit Il17rb." (PMID 30238872, 2018). "It is well established that tuft cells in the intestine respond to parasitic infections by secreting IL-25, which alerts nearby lymphoid cells, specifically ILC2s." (PMID 40395933, 2025). "Tuft cells have become key sentinels in parasitic infections by releasing alarmin IL-25, which activates ILC2 and enhances the type 2 immune responses, signaling the presence of worms." (PMID 40069907, 2025). "In mice with a specific knockout of intestinal epithelial IL-25, the proliferative responses of tuft cells and goblet cells induced by parasite infection were significantly diminished." (PMID 40356895, 2025). "For parasitic infections, IL-25 promotes the clearance of parasites, including worms, T. gondii, plasmodium, etc.." (PMID 39261649, 2024). "EC cells secrete serotonin (5-HT, a neurotransmitter) with diverse gastrointestinal functions and tuft cells (chemosensory epithelial cells) secrete interleukin-25, driving the type 2 immune response to parasitic infection." (PMID 38036781, 2023). "In the context of parasite infection, the tuft cell lining in the epithelium has been revealed as a dominant source of intestinal IL-25 and possesses the capability to regulate ILC2 homeostasis." (PMID 35707544, 2022). "Our data is in agreement with previous reports of ILC2s in the intestine, where IL-25 produced by Tuft cells further activated these cells to produce IL-13 in a parasitic infection context." (PMID 35711429, 2022). "So far, the roles of IL-25 contributing to the pathogenesis of arthropod parasites infection are not fully understood, and increased attention is requisite." (PMID 36119076, 2022). "In the steady state and after parasite infections, ILC2s produce growth factors of goblet cells, such as interleukin 13 (IL-13), in response to interleukin-25 (IL-25) secreted from Tuft cells." (PMID 34512636, 2021). "Previous studies have demonstrated that the migration of intestinal ILC2s stimulated by IL-25 or parasite infection is S1P dependent." (PMID 34305911, 2021). "Recent studies have shown that intestinal tuft cells activate group 2 innate lymphoid cells (ILC2) by secreting interleukin-25 (IL-25), followed by parasite infection." (PMID 34360687, 2021). "Given the important role of Lrmp in modulating Ca2+ flux in cells, we examined the levels of IL-25 in Lrmp−/− mice in response to parasitic infections and the succinate treatment." (PMID 34099671, 2021). "Upon the parasitic infections, tuft cells, a rare cell population (<1%) in the intestine, sense parasites and secret the cytokine IL-25." (PMID 34099671, 2021). "In the gut, it has been shown that tuft cell-derived IL-25 is required to mount a Th2 immune response to parasite infection." (PMID 32116793, 2020). "Several groups have independently shown that intestinal tuft cells sense and repel parasite infection through the expression of succinate receptor 1 and secretion of cytokine IL-25." (PMID 32116793, 2020). "ILC2 are also mostly tissue-resident lymphocytes and their effector-functions are triggered by interleukin (IL)-25 and IL-33 produced by epithelial cells or other immune cells in response to parasite infections or to allergen exposure." (PMID 31849972, 2019).
parasitic infection (continued). "In line with the idea that several organs are affected by parasitic infections, a global induction of IL-25 secreting tuft cells following parasitic infection, emphasizes the role of IL-25-mediated activation of ILC2 across extra-intestinal locations." (PMID 31574995, 2019). "In the gastrointestinal tract, TRPM5-expressng tuft cells release the cytokine interleukin-25 to initiate type 2 immunity against parasite infection." (PMID 29615870, 2018). "How tuft cells sense the signals from parasitic infection to initiate the production of IL-25 is still unclear." (PMID 28717211, 2017). "Intestinal tuft cells are one of 4 secretory cell linages in the small intestine and the source of IL-25, a critical initiator of the type 2 immune response to parasite infection." (PMID 28717211, 2017). "Reports have shown that IL-25 was a potent regulator of inflammation, contributing to allergic inflammation and protection against parasitic infection." (PMID 26840565, 2016). "Alarmin cytokines including IL-25, IL-33, and thymic stromal lymphopoietin (TSLP) function as danger signals to trigger host immunity in response to tissue injury caused by pathogenic factors such as parasitic infections." (PMID 39559705, 2024). "Furthermore, recently the enteric epithelial tuft cells produce IL-25 which is crucial for protection against parasite infection." (PMID 35061718, 2022). "In addition, IL-25 was downregulated in mice infected with Plasmodium berghei (P. berghei), and the incidence of parasitemia in the Il-25 depleted mice were higher than that in the wild-type mice." (PMID 36119076, 2022). "The probiotic treatment significantly increased mRNA expression of genes associated with enhanced protection against parasitic infection, including IL-25, RETNLB, and SOCS3, and did not interfere with the normal expulsion of L4 from the jejunum." (PMID 35335620, 2022). "In response to parasitic infections, tuft cells release IL-25 to trigger type 2 immunity." (PMID 34099671, 2021). "Indeed, gut-resident ILC2 can migrate into the lung and other peripheral tissues in response to helminthes or upon IL-25 stimulation to either fight the parasite infections or to contribute to tissue repair." (PMID 31849972, 2019). "Furthermore, IL-25 may also have anti-inflammatory effects in parasites infection, type 1 diabetes and systemic lupus erythematosus." (PMID 36119076, 2022). "Previous research has demonstrated that tuft cell-derived IL-25 regulates intestinal ILC2 and goblet cells in the epithelial response circuit during parasitic infections." (PMID 37937994, 2023). "Collectively, these observations suggest that the role of IL-25 in TH2 polarization is bypassed by multiple nonredundant mechanisms generated in vivo during parasite infection and allergic inflammation." (PMID 32179159, 2020). "The function of tuft cells was rather unclear until three studies recently demonstrated that tuft cells initiated type II immune response by secreting the cytokine IL25, IL33, and TSLP (thymic stromal lymphopoietin) following parasite infections in the murine intestine." (PMID 29163195, 2017). "Infected mice deficient in IL-13 or STAT6 did not reduce SFB or IL-17, and exogenous IL-25 replicated the effects of parasite infection in wild type mice." (PMID 26377648, 2015). "Additionally, RV infection modified the immune functional characteristics of tuft cells; unlike the response to parasitic infection, RV infection decreased the expression of the antiparasitic cytokine IL-25." (PMID 40356895, 2025).